PKDREJ (polycystin family receptor for egg jelly)
Description:
Testis-specific protein that controls sperm transport and the timing of zona pellucida-evoked exocytosis of the sperm acrosome.
Tractability: Antibody: UniProt places it where antibodies can reach, with medium confidence; UniProt predicts a signal peptide or a membrane-spanning region; its Gene Ontology location is reachable by antibodies, with medium confidence.
Gene: Protein-coding gene on chromosome 22 (46,255,663 to 46,263,343, reverse strand). Ensembl gene ENSG00000130943.
Subcellular location: Cell membrane; Cytoplasmic vesicle, secretory vesicle, acrosome membrane; Nucleus
Gene Ontology:
Molecular function: calcium channel activity; calcium ion binding
Biological process: acrosome reaction; detection of mechanical stimulus; calcium ion transmembrane transport
Cellular component: nucleus; membrane; plasma membrane; acrosomal membrane
Genetic constraint (gnomAD): Loss-of-function variants: 1 observed, 2.01 expected, observed/expected ratio (o/e) 0.5, 90% interval 0.17 to 1.74. That is too few expected variants to judge how well the gene tolerates losing a copy. Missense variants: 2,507 observed, 2,833.5 expected, observed/expected ratio (o/e) 0.88, 90% interval 0.86 to 0.91. Synonymous variants: 1,031 observed, 1,103.2 expected, observed/expected ratio (o/e) 0.93, 90% interval 0.89 to 0.98.
Homologues: Orthologues: chimpanzee PKDREJ (99% identical), macaque PKDREJ (94% identical), rabbit PKDREJ (63% identical), dog PKDREJ (61% identical), mouse Pkdrej (60% identical), rat Pkdrej (59% identical), guinea pig PKDREJ (56% identical), zebrafish pkd1l2a (19% identical), zebrafish pkd1a (17% identical), zebrafish pkd1l2b (16% identical), Drosophila melanogaster Pkd2 (5% identical), Caenorhabditis elegans pkd-2 (5% identical), and 1 more. Paralogues in human: PKD1 (19% identical), PKD1L2 (16% identical), PKD1L1 (14% identical), PKD1L3 (12% identical), LOXHD1 (10% identical), DENND5B (8% identical), DENND5A (7% identical), PKD2 (7% identical), PKD2L1 (6% identical), PKD2L2 (5% identical).
Diseases named in the same sentence as PKDREJ in open-access papers:
PKDREJ is named in the same sentence as 2 diseases in open-access papers, as found by Europe PMC text mining. Sharing a sentence is not in itself a finding about the gene and the disease.
PKDREJ shares sentences with these, for which no sentence is quoted: kidney disease (2 papers); polycystic kidney disease (1).